BAG6 (BAG cochaperone 6)
Diseases named in the same sentence as BAG6 in open-access papers (continued):
Sharing a sentence is not in itself a finding about the gene and the disease.
cholangiocarcinoma (2 papers, 2024 to 2025). A carcinoma that arises from the intrahepatic biliary tree (intrahepatic cholangiocarcinoma) or from the junction, or adjacent to the junction, of the right and left hepatic ducts (hilar cholangiocarcinoma). "It has been implicated in cancer cell survival, tumor progression and chemotherapy resistance in cholangiocarcinoma via stabilizing BAG6." (PMID 40718795, 2025).
diabetes (2 papers, 2019 to 2020). "The mammalian Bag6/Bat3 gene has been suggested to be linked with potential obesity- and diabetes-associated loci, while its function in the control of glucose incorporation into the cytoplasm has not been investigated." (PMID 31911483, 2020).
endometriosis (2 papers, 2018 to 2026). The growth of functional endometrial tissue in anatomic sites outside the uterine body. "Eutopic endometrium from women with endometriosis in the secretory phase showed significantly higher immunoexpression scores for BAG6 supporting our in silico data." (PMID 30021652, 2018). "NKp30 (NCR3) and its ligand BAT3 (BAG6) were significantly upregulated in 6/6 and 4/6 secretory phase datasets from endometriosis patients respectively compared with control patients (1.2–1.7 fold change and 1.4–2.3 fold change respectively)." (PMID 30021652, 2018). "Immunohistochemical staining scores for BAG6 was also significantly higher in secretory phase eutopic endometrium from women with endometriosis compared with the endometrium of healthy women (n = 8/group)." (PMID 30021652, 2018). "We have demonstrated that human endometrium expresses BAG6 protein for the first time, and revealed an increased immuno-expression for BAG6 in secretory endometrium of women with endometriosis validating our in silico study." (PMID 30021652, 2018). "Published eutopic endometrial microarray datasets demonstrated significant upregulation of NKp30 and its ligand BAG6 in women with endometriosis compared with controls." (PMID 30021652, 2018). "In silico data was validated by examining the secretory phase eutopic endometrium of women with and without endometriosis (n = 8/group) for the immuno-expression of BAG6 protein." (PMID 30021652, 2018).
glioblastoma (2 papers, 2024 to 2025). The most malignant astrocytic tumor (WHO grade IV). "Similarly, our subsequent analysis of single-cell RNA-Seq data from Neftel and colleagues revealed that HAVCR2 (TIM-3) expression was detected in most T cells (81%) in the glioblastoma micro-environment and was correlated with low expression of BAG6 (BAT3)." (PMID 39513882, 2024).
idiopathic male infertility (2 papers, 2021 to 2024). "Interestingly, the interaction of HSPA2 with BAG6 (BCL2-associated athanogene 6; formerly BAT3, HLA-B-associated transcript 3) has been demonstrated to regulate its stability thereby making BAG6 a molecular target for idiopathic male infertility." (PMID 39005499, 2024). "Previous research has indicated that BAG6 and HIST1H2BA are potential candidates as male infertility biomarkers." (PMID 34330296, 2021).
metastatic melanoma (2 papers, 2019 to 2024). A melanoma that has spread from its primary site to another anatomic site. "Highlighting the importance of BAG6-regulated EVs, we detected (tumor-promoting) vesicular α-catulin mRNA (enriched in mouse BAG6KO-EVs compared to WT-EVs) exclusively in late stage EVs from metastatic melanoma patients, and this correlated inversely with the cellular BAG6 transcript expression." (PMID 31534536, 2019).
Obesity (2 papers, 2020 to 2023). Accumulation of substantial excess body fat. "The Bag6 gene [also called Bat3 in humans] is linked to potential obesity loci, and differential alternative splicing of Bag6 transcript is observed between overweight individuals with type 2 diabetes and lean individuals with normal glycemia." (PMID 31911483, 2020). "It was recently suggested that Bag6 is encoded within potential obesity susceptibility loci on chromosome 6p21, and a significant difference in the alternative splicing of Bag6 transcripts was observed between overweight individuals with type 2 diabetes and lean individuals with normal glycemia." (PMID 31911483, 2020). "Given that Rab8a-family small GTPases and Stx6 are critical for GLUT4 translocation, we suggest that BAG6 may play multiple roles in glucose incorporation; thus, a deficiency of this triage factor might be a potential cause for some classes of obesity and type 2 diabetes." (PMID 31911483, 2020). "Furthermore, Hager and colleagues assessed the role of genetic variation in determining protein level variation in obesity and suggested that rare polymorphisms in the Bag6 gene might be associated with the observed changes in leptin protein expression in subjects with type 2 diabetes." (PMID 31911483, 2020).
sarcopenia (2 papers, 2020 to 2025). Progressive decline in muscle mass due to aging which results in decreased functional capacity of muscles. "MMP24‐AS1, HLA‐DRB6, HLA‐DQA2, DDX42, BAG6, NUSAP1, LINC00940, NME1‐NME2 and AS3MT in the amygdala region showed detrimental effect on all the five sarcopenia‐related traits, whereas HLA‐DRB1, HLA‐DQB1‐AS1 and C6ORF3 showed protective effect (p < 0.05)." (PMID 39535371, 2025). "The over‐expression of nine genes (MMP24‐AS1, HLA‐DRB6, HLA‐DQA2, DDX42, BAG6, NUSAP1, LINC00940, NME1‐NME2 and AS3MT) in the amygdala region showing detrimental effect on all the five sarcopenia‐related traits, whereas three genes (HLA‐DRB1, HLA‐DQB1‐AS1 and C6ORF3) showing protective effect." (PMID 39535371, 2025).
tuberculosis (2 papers, 2012 to 2014). A chronic, recurrent infection caused by the bacterium Mycobacterium tuberculosis. "The present study characterizes epidemiologically the association between genetic variants in exon 2 of the FAM46A gene, a genetic marker in BAG6 gene and tuberculosis in a case-control study in a Croatian Caucasian population." (PMID 24625963, 2014). "Therefore, we used a candidate gene approach to study the association of human FAM46A and BAG6 genes with tuberculosis." (PMID 24625963, 2014). "We analyzed for association between the Family with sequence similarity 46, member A (FAM46A) gene (located on chromosome 6q14.1), BCL2-Associated Athanogene 6 (BAG6) gene (located on chromosome 6p21.3) and tuberculosis in Croatian Caucasian." (PMID 24625963, 2014). "This may suggests that the interaction between the FAM46A and BAG6 proteins may be involved in tuberculosis etiology." (PMID 24625963, 2014). "Thus, we speculate that the FAM46A and BAG6 proteins interaction may play an important role in tuberculosis etiology." (PMID 24625963, 2014).
autoimmune disease (1 paper, 2017). A disorder resulting from loss of function or tissue destruction of an organ or multiple organs, arising from humoral or cellular immune responses of the individual to their own tissue constituents. "BAG6 rescues Th cells from exhaustion and its overexpression can lead to increased risk for autoimmune diseases in mice." (PMID 28081217, 2017).
B cell lymphoma (1 paper, 2019). "In fact, re-expression of BAG6 and CBP/p300 upon inhibition of the transcriptional repressor BCL6 rendered B cell lymphoma cells and xenografts susceptible to HDACi and HSP90 therapy." (PMID 31534536, 2019).
basal cell carcinoma (1 paper, 2019). A carcinoma involving the basal cells. "In addition, BAG6 is implicated in the control of apoptosis and is associated with basal cell carcinoma." (PMID 31888641, 2019).
celiac disease (1 paper, 2021). An autoimmune genetic disorder with an unknown pattern of inheritance that primarily affects the digestive tract. "The MHC signal is independent of known HLA associations with ulcerative colitis and celiac disease; in fact, it localizes to BAG6." (PMID 34741163, 2021).
cervical cancer (1 paper, 2025). A primary or metastatic malignant neoplasm involving the cervix. "Notably, BAG2 expression was significantly reduced in cervical cancer, while no significant changes were observed in other BAG family members (BAG1, BAG3, BAG4, BAG5, and BAG6), suggesting a unique role for BAG2 in cervical cancer." (PMID 40364789, 2025).
Coronary arteriosclerosis (1 paper, 2024). "Coronary arteriosclerosis shared 10 GWS genes with AD (BAG6, C6orf10, HLA-DQB1, HLA-DRA, HLA-DRB1, NDUFAF6, NME7, PLCG2, PRRC2A, and TRIB1), while myocardial infarction shared three genes with AD (HLA-DRA, PHB, and RP11-81K2.1)." (PMID 39201500, 2024).
Hodgkins lymphoma (1 paper, 2021). A heterogeneous group of malignant lymphoid neoplasms of B-cell origin characterized histologically by the presence of Hodgkin and Reed-Sternberg (HRS) cells in the vast majority of cases. "NK cell function impairment was also explored in Hodgkin lymphoma (HL), where it correlated with elevated serum levels of soluble ligands for NK cell receptors NKp30 (BAG6/BAT3) and NKG2D (MICA), which are known to constrict NK cell function." (PMID 34203935, 2021).
Hypertension (1 paper, 2022). The presence of chronic increased pressure in the systemic arterial system. "In this cohort of subjects, two SNPs of hypertension/BP genes (rs805303 of the BAG6 and rs167479 of the RGL3) were associated with PE." (PMID 36556383, 2022). "According to data from earlier GWAS, rs805303 of BAG6 was associated with levels of both systolic and diastolic BP and hypertension, and rs167479 of RGL3 was associated with BP (systolic, diastolic and pulse, and mean arterial pressure) and hypertension." (PMID 36556383, 2022).
lymphocytic leukemia (1 paper, 2020). "On the other hand, while the NKp30 ligand soluble BAG6, released by lymphocytic leukemia cells, works as an inhibitory ligand of NKp30, exosome-bound BAG6 activates NK cells in chronic lymphocytic leukemia (CLL)." (PMID 32218226, 2020).
lymphoma (1 paper, 2013). A malignant (clonal) proliferation of B- lymphocytes or T- lymphocytes which involves the lymph nodes, bone marrow and/or extranodal sites. "Based on the gene expression studies, we identified BAT3/BAG6, HIGD1A, and FAT10/UBD as immunohistochemical markers expressed in the tumor cells of all three lymphomas." (PMID 24244368, 2013).
osteoporosis (1 paper, 2024). A condition of reduced bone mass, with decreased cortical thickness and a decrease in the number and size of the trabeculae of cancellous bone (but normal chemical composition), resulting in increased fracture incidence. "Moreover, increased expression of exosomal BAG6 was observed in patients with osteoporosis compared with that in normal subjects." (PMID 38088531, 2024).
pancreatic ductal adenocarcinoma (1 paper, 2024). An infiltrating adenocarcinoma that arises from the epithelial cells of the pancreas. "We used a Cre recombinase/LoxP-based reporter system in combination with single-cell RNA sequencing to monitor in vivo EV uptake and tumor microenvironment (TME) changes in mouse models for pancreatic ductal adenocarcinoma (PDAC) in a Bag6 pro- or deficient background." (PMID 38942797, 2024).
Pleural effusion (1 paper, 2025). The presence of an excessive amount of fluid in the pleural cavity. "The results showed that CXCL16 was significantly higher in the MPE of LCP than in the pleural effusion of HP, whereas BAG6 and IL-7 did not exhibit statistically significant difference." (PMID 40959273, 2025).
proteinopathies (1 paper, 2022). "In efforts to identify additional PQC mechanisms that participate in protecting cells from proteinopathies, we found that the molecular chaperone, BAG6, functions as an intracellular sensor of solvent-exposed hydrophobicity in proteolytic fragments." (PMID 35542047, 2022).
pulmonary tuberculosis (1 paper, 2014). A bacterial infection that affects the lungs and is caused by Mycobacterium tuberculosis. "The FAM46A gene could therefore be a potential candidate that determines the risk of developing pulmonary tuberculosis in some individuals on its own or in association with other genes such as BAG6." (PMID 24625963, 2014).
rheumatic diseases (1 paper, 2025). "It has been discovered that some of these genes (C2, BX511262.2, PRRC2A, BAG6, PBX2, GPSM3, NELFE and AIF1) are significant genetic targets shared by MetS and multiple rheumatic diseases." (PMID 39789419, 2025).
schizophrenia (1 paper, 2025). A major psychotic disorder characterized by abnormalities in the perception or expression of reality. "The microglial H-MAGMA-risk genes BAG6, NEU1, PRRC2A, PSMB8, PSMB8-AS1 and PSMB9 were associated with MS, ALS and schizophrenia." (PMID 40202986, 2025).
tumor (72 papers, 2012 to 2025). "Studies have shown that BAG6 can be secreted in two distinct forms: extracellular vesicle-associated BAG6 (EV-BAG6) and soluble BAG6 (sBAG6), which have opposing effects on tumor immune evasion." (PMID 40959273, 2025). "BAG6-mediated immune modulation and IL-7's dual effects on tumor progression were also linked to poor survival." (PMID 40959273, 2025). "BCL2-associated athanogene 6 (BAG6) plays a multifaceted role in cellular physiology and tumor progression, including protein quality control, immune regulation, and apoptosis." (PMID 40959273, 2025). "Bag6-deficiency allowed the release of EV-associated IL33 which modulate the TME via MC activation promoting aggressive tumor growth." (PMID 38942797, 2024). "For instance, a recognised mechanism of tumor escape in is the shedding of soluble ’decoy’ ligands for NK cell activating receptors, including BCL2-associated athanogene 6 (BAG-6) and B7-H6." (PMID 31438563, 2019). "Here, we investigated the role of the chaperone Bcl2-associated anthogene 6 (BAG6, synonym Bat3) for the formation of pro- and anti-tumor EVs." (PMID 31534536, 2019). "Clarification of the linkage between defects in the metabolism of BAG6 clients and various human diseases linked to tumor etiology, neurodegenerations, and defective immune responses will be a relevant prospect for extensive future investigations." (PMID 29109525, 2017). "Here, exosomal BAG6 was essential for tumour cell killing because BAG6-deficient cells evaded immune detection." (PMID 26082317, 2013). "Bag6-deficient tumors grew much faster compared to Bag6-expressing tumors and were characterized by decreased T cell infiltration and accumulation of inflammatory cancer-associated fibroblasts (iCAFs) indicative of a tumor-promoting TME." (PMID 38942797, 2024). "Depletion of MCs using imatinib restricted tumor development in a Bag6-deficient mouse model, indicating that patients with low BAG6 expression and high MC infiltration may benefit from imatinib therapy (see graphical abstract for summary)." (PMID 38942797, 2024). "Likewise, the presence of BCL2-associated Athanogene 6 (BAG-6), one of the NKp30 ligands, in the tumor cell membrane or exosomes stimulates NK cell antitumor activity whereas its soluble form hampers NK cell function." (PMID 35990652, 2022). "Thus, the NKp30-ligand HLA-B-associated transcript-3/BCL-2-associated athanogene 6 (BAT3/BAG6) is a nuclear factor that can be released via exosomes and exposed at the cell surface by many tumor cells or, in response to stress, by DCs." (PMID 24678311, 2014). "They mediate cytotoxicity and tumor cell lysis through interactions with their respective ligands, such as human leukocyte antigen (HLA)‐B‐associated transcript 3/Bcl‐2‐associated athanogene 6 (BAT3/BAG6), mixed‐lineage leukemia 5 (MLL5), and ecto‐calreticulin (ecto‐CRT)." (PMID 40959206, 2025). "Our data demonstrated that Bag6-deficient subcutaneous and orthotopic PDAC tumors accelerated tumor growth dependent on EV release." (PMID 38942797, 2024). "This revealed a hitherto unreported tumor-suppressive role of BAG6 in PDAC which was attributed to its role in the formation and release of EVs." (PMID 38942797, 2024). "Pan02 Bag6 knock-out (Bag6 KO) and Pan02 wild-type tumor cells (Bag6 WT) were transplanted into immune-competent mice." (PMID 38942797, 2024). "We first validated Bag6 expression and cre-mRNA expression in tumor cells by Western blotting and PCR, respectively." (PMID 38942797, 2024). "MC depletion using imatinib diminished tumor growth providing a scientific rationale to consider imatinib for patients stratified with low BAG6 expression and high MC infiltration." (PMID 38942797, 2024).